GAPDH (glyceraldehyde-3-phosphate dehydrogenase)
Diseases named in the same sentence as GAPDH in open-access papers (continued):
Sharing a sentence is not in itself a finding about the gene and the disease.
salivary gland tumors (1 paper, 2024). "Some of the identified peptides were derived from proteins previously suggested as potential biomarkers of salivary gland tumors (ANXA1, BPIFA2, FGB, GAPDH, HSPB1, IGHG1, VIM) or tumors of other tissues or organs (SERPINA1, APOA2, CSTB, GSTP1, S100A8, S100A9, TPI1)." (PMID 39201484, 2024).
sarcoidosis (1 paper, 2008). Sarcoidosis is a multisystemic disorder of unknown cause characterized by the formation of immune granulomas in involved organs. "Finally, to demonstrate effect of traditional (ACTB/GAPDH) and novel (PSMB2/RPL32) reference genes as denominators, expression of two cytokines known associated with sarcoidosis was investigated in sarcoid BAL cells." (PMID 18671841, 2008). "Similar, when CCL2 mRNA levels were expressed as a ratio to ACTB (1.00 ± 0.85; p = 0.46) or to GAPDH (1.37 ± 0.98; p = 0.43), there were not significant differences in mRNA levels in BAL cells between sarcoidosis patients with chest radiographic stage 2 and stage 1 patients." (PMID 18671841, 2008).
Senile plaques (1 paper, 2021). Senile plaques are extracellular deposits of amyloid in the gray matter of the brain. "Among the glycolytic enzymes, glyceraldehyde-3-phosphate dehydrogenase (GAPDH) and enolase are frequently found in senile plaques." (PMID 34454574, 2021).
septic arthritis (1 paper, 2022). "For the first time, we demonstrate that DMF leads to bacteriostatic effects on MRSA by directly targeting GAPDH, thereby inhibiting MRSA proliferation and biofilm formation, with potential adjunctive utility in the treatment of septic arthritis." (PMID 36354099, 2022).
serous adenocarcinoma (1 paper, 2013). An adenocarcinoma that is characterized by the presence of papillary patterns and cellular budding. "Our data indicate that high GAPDH as well as low BEC-index based on mRNA are associated with early disease progression in patients with advanced high-grade serous adenocarcinomas of the ovary, fallopian tube or peritoneum." (PMID 24252137, 2013). "Our findings indicate that GAPDH and BEC-index may identify groups of advanced high-grade serous carcinomas with different prognosis." (PMID 24252137, 2013).
staphylococcal infection (1 paper, 2011). An infection caused by Staphylococcus. "Some of them have been tested as vaccine target to prevent staphylococcal infections e.g., Enolase (Eno), IsdA (an iron-regulated cell wall-anchored protein) and IsdB (a cell surface transferrin-binding protein), GapC/B protein (glyceraldehyde-3-phosphate dehydrogenase), Hla (alpha-hemolysin)." (PMID 21324116, 2011).
stomach adenocarcinomas (1 paper, 2019). "According to the obtained results, GAPDH can be reasonably applied as a RG only in prostate and stomach adenocarcinomas." (PMID 30881377, 2019).
systemic sclerosis (1 paper, 2020). A chronic disorder, possibly autoimmune, marked by excessive production of collagen which results in hardening and thickening of body tissues. "Giusti and co-authors analyzed the proteome of whole saliva in patients with systemic sclerosis and observed elevated GAPDH in patients compared to controls." (PMID 32272779, 2020).
testicular seminoma (1 paper, 2019). A malignant germ cell tumor arising from the testis. "In testicular seminoma tissues, the TDRG1/GAPDH ratio increased to 0.23 ± 0.02 (P < .001) and the LC3‐II/GAPDH ratio increased to 0.18 ± 0.01 (P < .001)." (PMID 31496041, 2019).
Thiamine deficiency (1 paper, 2020). Thiamine deficiency is a condition that occurs due to not enough thiamine (vitamin B1). "In a QTOF-based study of rat thalami under thiamine deficiency, glyceraldehyde-3-phosphate dehydrogenase (GAPDH) is the most up-regulated protein (50 fold) while regulated proteins are most enriched in the synaptic vesicle cycle pathway (according to the KEGG database)." (PMID 32863845, 2020).
tongue tumor (1 paper, 2018). "Among 24 candidates, 8 proteins including Myosin light chain family members (MYLPF, MYL4 and MYL2), creatinine kinase, serotransferrin, heat shock protein A8, carbonic anhydrase 1 and Glyceraldehyde-3-phosphate dehydrogenase were significantly downregulated in tongue tumor tissues." (PMID 29371635, 2018).
triple-negative breast carcinoma (1 paper, 2021). An invasive breast carcinoma which is negative for expression of estrogen receptor (ER), progesterone receptor (PR), and human epidermal growth factor receptor 2 (HER2). "GSTP1 directly binds to glyceraldehyde-3-phosphate dehydrogenase (GAPDH) and activates its glycolytic enzyme function in triple-negative breast cancer cells, as demonstrated by pharmacological inactivation." (PMID 34209254, 2021).
urothelial carcinoma (1 paper, 2024). A malignant neoplasm derived from the transitional epithelium of the urinary tract (urinary bladder, ureter, urethra, or renal pelvis). "Urine samples from dogs diagnosed with urothelial carcinoma were tested, and conventional PCR was used to detect both the wild-type (Wt) and mutant (Mu) BRAF V595E mutation in the urine samples, with GAPDH serving as an internal control." (PMID 39272320, 2024).
viral hepatitis (1 paper, 2012). An acute or chronic inflammation of the liver parenchyma caused by viruses. "The involvement of GAPDH in several hepatocarcinogenic mechanisms (e.g. viral hepatitis, metabolic alterations) and its sensitivity to a new class of prospective anticancer agents prompted us to review the current understanding of the therapeutic potential of targeting GAPDH in HCC." (PMID 22964488, 2012).
Wiskott-Aldrich syndrome (1 paper, 2020). Wiskott-Aldrich syndrome (WAS) is a primary immunodeficiency disease characterized by microthrombocytopenia, eczema, infections and an increased risk for autoimmune manifestations and malignancies. "DAPI, 4’,6-diamidino-2-phenylindole; GAPDH, glyceraldehyde 3-phosphate dehydrogenase; HC, healthy control; MDM, monocyte-derived macrophage; SEM, standard error of the mean; WAS, Wiskott Aldrich syndrome." (PMID 33135633, 2020). "DAPI, 4’,6-diamidino-2-phenylindole; GAPDH, glyceraldehyde 3-phosphate dehydrogenase; HC, healthy control; IQR, interquartile range; MDM, monocyte-derived macrophage; ns, not significant; SDM, stem-cell-derived macrophage; SEM, standard error of the mean; WAS, Wiskott Aldrich syndrome." (PMID 33135633, 2020).
tumor (467 papers, 2002 to 2026). "Second, GAPDH gene variants in the human genome induce pseudogene expression, especially in tumor and aging tissues." (PMID 39741957, 2024). "The most highly expressed coding RNAs encode a glycine-rich protein, glyceraldehyde-3-phosphate dehydrogenase, protein-synthesizing GTPase, Bet v I-type allergen, translationally controlled tumor protein, and a hypothetical protein." (PMID 38475449, 2024). "Regarding the association between Warthin’s tumor and GAPDH, on anti-GAPDH immunohistochemical staining, Warthin’s tumor cells had a significantly lower percentage of GAPDH-positive cells (p < 0.0001) in comparison to normal parotid duct cells." (PMID 38473274, 2024). "Inducing senescence in LKB1-deficient non-small cell lung cancer cells through GAPDH depletion suggests a novel strategy for controlling the proliferation of tumor cells." (PMID 39744129, 2024). "We therefore asked if loss of the GAPDH redox switch would make tumour cells more responsive to chemotherapy." (PMID 37024754, 2023). "Tumours harbouring oxidation-resistant GAPDH grew significantly slower, suggesting that the loss of the GAPDH redox switch was a disadvantage for the tumour." (PMID 37024754, 2023). "In a subsequent analysis of the association between GAPDH and clinical characteristics, we found that GAPDH expression was higher in male patients, and GAPDH was positively associated with tumor metastasis and progression." (PMID 36837761, 2023). "GAPDH is one of the enzymes associated with glycolysis, and overexpression of GAPDH is associated with tumor development." (PMID 37175615, 2023). "A few reports indicate that proliferation and invasion are linked to increased GAPDH expression in some tumor cells." (PMID 36837761, 2023). "In other words, the GAPDH redox switch helps tumour cells to activate the oxPPP and to suppress the oxidative stress that is associated with tumour growth." (PMID 37024754, 2023). "Reduced GAPDH expression in tumors slows the glycolytic pathway, interfering with the energy metabolism of the tumor and enhancing the death of tumor cells caused by ferroptosis." (PMID 36837761, 2023). "Subsequently, we discovered a positive correlation between high GAPDH expression and the number of overall tumor mutations." (PMID 36837761, 2023). "Actually, in the past decades, the protein markers that were highly suppressed by dasatinib including GAPDH, tubulin, cyclophilin B and cofilin have been found to be closely associated with tumor metastasis." (PMID 36559193, 2022). "It therefore appears possible that GAPDH loss in Warthin tumor oncocytes affects regular mitophagy, leading to the typical accumulation of aged, dysfunctional mitochondria." (PMID 32365590, 2020). "GAPDH was shown to be involved in regulation of tumor cell glycolysis and autophagy and was also linked to microenvironment-associated hypoxia." (PMID 33194682, 2020). "How reduction or loss of GAPDH in Warthin tumor oncocytes affects tumor cell metabolism is unclear and requires further studies." (PMID 32365590, 2020). "Another important mechanism triggered by GAPDH in starving tumor cells is autophagy linked to Sirt1 activation." (PMID 32370188, 2020). "GAPDH is deregulated in various cancer cells, and it is a new therapeutic target associated with tumor progression." (PMID 28410203, 2017). "In human HCC, the increased expression of GAPDH is invariably associated with enhanced glycolytic capacity facilitating tumor progression." (PMID 22964488, 2012). "Metabolically, in human HCC, the increased expression of GAPDH is invariably associated with increased glycolytic capacity, facilitating tumor progression." (PMID 22964488, 2012). "In addition, studies pointing to its involvement in apoptosis-promoting functions and tumor progression have suggested that GAPDH depletion is associated with cellular senescence, such as accelerated senescence in tumor cells." (PMID 38473274, 2024).
tumor (continued). "Apart from clinical features, we wondered whether GAPDH expression was associated with the tumor immune microenvironment." (PMID 36837761, 2023). "Indeed, we found that cisplatin as well as radiation treatment, both of which elevated endogenous peroxide levels in tumour cells, strongly enhanced the tumour-suppressive effect of a deficient GAPDH redox switch." (PMID 37024754, 2023). "Investigations have examined GAPDH’s interaction with mutated KRAS and BRAF, suggesting that GAPDH suppression via vitamin C may disrupt tumor growth." (PMID 38134011, 2023). "GAPDH has previously been associated with tumor progression." (PMID 36982192, 2023). "The evidence suggests that GAPDH function mechanisms, such as its role in cell survival of tumor, angiogenesis, and posttranscriptional regulation of tumor cell mRNA, are associated with poor prognosis and increased tumor progression for the affected individual." (PMID 35880695, 2023). "Hence, silencing GAPDH suppresses the proliferating capacity of tumor cells and causes cancer cell apoptosis." (PMID 36077431, 2022). "In hypoxic conditions, a disruption of the Hsp70-mediated GAPDH chaperoning led to subsequent denaturation and aggregation of the enzyme that may cause the death of tumor cells." (PMID 33546324, 2021). "The present study could demonstrate a characteristic immunohistochemical GAPDH staining pattern in Warthin tumor oncocytes pointing to a progressive loss of cytoplasmic GAPDH which appeared to be due to total cellular loss or nuclear shift of the protein." (PMID 32365590, 2020). "Increased enzymatic activity of GAPDH in tumor cells may be attributed to its association with PKM2 and GPI." (PMID 26911935, 2016). "The marker rs7971637 in GAPDH was associated with tumour stage T3/T4 (OR = 1.60, 95% CI 1.11–2.30)." (PMID 22545919, 2012). "Studies indicate that GAPDH harbors an active site cysteine residue susceptible to oxidation under hydrogen peroxide, resulting in rapid enzyme inactivation, with its redox-switching activity serving to preserve reductive capacity and promote the survival of stressed tumor cells." (PMID 39268462, 2024). "Furthermore, the number of tumor mutations is strongly linked to high GAPDH expression." (PMID 36837761, 2023). "Indeed, analysis of two FH-deficient cell lines—UOK 262 and NCCFH1—as well as FH-deficient tumor, showed strong succination of various, functionally important proteins, including glyceraldehyde 3-phosphate dehydrogenase (GAPDH) and Kelch-like ECH-associated protein 1 (Keap1)." (PMID 31963199, 2020). "GAPDH was used as an internal control,and relative expression levels in tumor samples were compared to thosein matched normal tissues." (PMID 41493269, 2026). "GAPDH is often overexpressed in human cancers, where it helps tumor survival by coordinating glycolysis (to produce ATP) and autophagy (to remove damaged mitochondria), thereby protecting cells from caspase-independent cell death." (PMID 40158853, 2025). "GAPDH is overexpressed in cancers and involved in many cancerous cellular processes, such as regulating apoptosis and tumor progression." (PMID 40076506, 2025). "GAPDH is one of the most prominent housekeeping proteins, involved in glycolysis and various tumor‐related biological processes." (PMID 41439108, 2025). "Specifically, studies have demonstrated that GAPDH and β-actin levels can be upregulated or downregulated depending on tumor type, grade, metabolic status, and cellular stress responses." (PMID 40565357, 2025). "Western blot analysis of 15 paired patient samples further confirmed the down-regulation of NR1D2 in tumor tissues relative to adjacent normal tissues, with consistent GAPDH expression validating experimental reliability (P < 0.001)." (PMID 41562084, 2025). "GAPDH antagonists induce apoptosis and inhibit tumor progression and GAPDH inhibition can overcome chemotherapy resistant responses." (PMID 40137165, 2025).
tumor (continued). "Immunoblotting of three representative pairs confirmed increased SOX2 and LPCAT1 protein in tumor relative to matched normal tissue, with GAPDH as loading control." (PMID 41358198, 2025). "GAPDH is frequently upregulated in highly glycolytic tumor cells and is considered a promising target in cancer metabolism." (PMID 41006687, 2025). "Stronger anticancer effect in animals with KRAS and BRAF mutant by decreasing intracellular glucose and energy production due to intracellular ROS accumulation and GAPDH inhibition compared wild type tumor (P < 0.05)." (PMID 40950984, 2025). "GAPDH involvement in cellular metabolism is essential for cancer cell proliferation and tumor development across multiple cancer types, and it also contributes to drug resistance." (PMID 41006687, 2025). "In contrast, TGF-β-3 expression, also normalized to GAPDH, was significantly elevated across tumor grades, increasing from 2.17 ± 0.42 in G2 to 4.54 ± 0.65 in G3 and 5.15 ± 1.09 in G4 (p < 0.05)." (PMID 40620718, 2025). "GAPDH expression is increased in stage 4 tumours when compared to stage 1 tumours in all datasets (****p < 0.0001 Cangelosi, Kocak, Asgharzadeh)." (PMID 41420301, 2025). "This process holds therapeutic potential, as studies suggest pharmacological induction of GAPDH oxidation shows promise for treating tumours." (PMID 40639322, 2025). "The glycolytic enzyme glyceraldehyde-3-phosphate dehydrogenase (GAPDH) has been found to be upregulated in different cancer types, suggesting its role in tumour development." (PMID 41175344, 2025). "Proliferation, and cytokine release and TCRB repertoire of from PDA patient peripheral T lymphocytes, before and after CT, were analyzed in vitro in response to four tumor-associated antigens (TAA), namely ENO1, FUBP1, GAPDH and K2C8." (PMID 39176093, 2024). "3BP significantly decreased intracellular oxygen consumption by downregulating hexokinase-II (HK-II) and glyceraldehyde 3-phosphate dehydrogenase (GAPDH) expression, consequently alleviating tumor hypoxia and enhancing the efficacy of PDT." (PMID 39209834, 2024). "In the LUAD_CPTAC_protein dataset, the expression of GAPDH in tumor tissue is significantly higher than in normal tissue (p < 0.001)." (PMID 38928396, 2024). "One recent study showed that GAPDH is commonly upregulated in various types of cancer and potentially required for cancer cell growth and tumour formation." (PMID 39641316, 2024). "Ct values of IGF2 and INS-IGF2 normalized to GAPDH, were used to calculate ΔCt values, and relative expression was derived by dividing 2−ΔCt for tumor vs adjacent normal tissue within each group." (PMID 39593106, 2024). "The quantitative analysis of the expression of GAPDH mRNA by quantitative RT-PCR also showed that Warthin’s tumor cells had lower expression levels in comparison to normal parotid duct cells." (PMID 38473274, 2024). "When only tumor samples are included, the correlation analysis based on tumor samples still shows significant positive correlations between GAPDH protein expression and IGF2BP1 (r = 0.455, p < 0.001)." (PMID 38928396, 2024). "Recently, a serum acylation system of GAPDH has been reported, which promotes the glycolytic metabolism and anti-tumor immune activity of CD8 T cells." (PMID 39268462, 2024). "BAMBI levels normalized to GAPDH were 1.1 ± 0.6 in non-tumor tissue and were 1.7 ± 2.0 (p = 0.198) in tumors." (PMID 39457709, 2024). "In this study, analysis of tumor cell stemness showed that a subset of tumor cells with higher stemness scores also exhibited upregulated expression levels of GAPDH, indirectly indicating increased exosome secretion activity." (PMID 39044829, 2024). "GAPDH directly participates in tumor progression, invasiveness, and metastasis, and conditions such as oxidative stress impair GAPDH catalytic activity, leading to cellular aging and apoptosis." (PMID 39267750, 2024).